CGB8 (chorionic gonadotropin subunit beta 8)
Description:
Beta subunit of the human chorionic gonadotropin (hCG). hCG is a complex glycoprotein composed of two glycosylated subunits alpha and beta which are non-covalently associated. The alpha subunit is identical to those in the pituitary gonadotropin hormones (LH, FSH and TSH). The beta subunits are distinct in each of the hormones and confer receptor and biological specificity. Has an essential role in pregnancy and maternal adaptation. Stimulates the ovaries to synthesize the steroids that are essential for the maintenance of pregnancy.
Gene: Protein-coding gene on chromosome 19 (49,047,638 to 49,049,125, reverse strand). Ensembl gene ENSG00000213030.
Subcellular location: Secreted
Pathways (Reactome):
Gene expression (Transcription): TFAP2 (AP-2) family regulates transcription of growth factors and their receptors
Metabolism of proteins: Glycoprotein hormones
Gene Ontology:
Molecular function: protein binding; hormone activity
Biological process: apoptotic process; cell-cell signaling; female gamete generation; G protein-coupled receptor signaling pathway; hormone-mediated signaling pathway; signal transduction; cell communication; signaling
Cellular component: extracellular region; pituitary gonadotropin complex
Genetic constraint (gnomAD): Loss-of-function variants: 2 observed, 5.21 expected, observed/expected ratio (o/e) 0.38, 90% interval 0.16 to 1.2. That is too few expected variants to judge how well the gene tolerates losing a copy. Missense variants: 15 observed, 76.94 expected, observed/expected ratio (o/e) 0.19, 90% interval 0.13 to 0.3. Synonymous variants: 8 observed, 26.81 expected, observed/expected ratio (o/e) 0.3, 90% interval 0.17 to 0.54.
Homologues: Orthologues: macaque CGB8 (80% identical), Drosophila melanogaster Gpb5 (16% identical). Paralogues in human: CGB3 (100% identical), CGB5 (100% identical), CGB7 (98% identical), CGB2 (97% identical), CGB1 (92% identical), LHB (70% identical), TSHB (30% identical), FSHB (26% identical), GPHB5 (22% identical).
Diseases named in the same sentence as CGB8 in open-access papers:
CGB8 is named in the same sentence as 9 diseases in open-access papers, as found by Europe PMC text mining. Sharing a sentence is not in itself a finding about the gene and the disease. The quoted sentences say what the papers report.
breast carcinoma (2 papers, 2017 to 2025). "CGB8, a member of the chorionic gonadotropin beta subunit family, promotes tumorigenesis and progression in breast cancer." (PMID 40416783, 2025). "The β-HCG genes CGB3, CGB5, CGB8 and CGB9, called type II β-HCG genes, were found to be expressed in 46% of breast cancer cases, but not in normal mammary epithelium." (PMID 28754015, 2017).
oral squamous cell carcinoma (1 paper, 2021). "Recent studies have shown that CGB8 could also be used as an immune-related prognostic model gene for oral squamous cell carcinoma (OSCC)." (PMID 34112138, 2021).
prostate carcinoma (1 paper, 2026). A carcinoma that arises from epithelial cells of the prostate gland. "While previous reports have linked CGB8 to ECM‐related pathways in prostate cancer, our findings suggest its broader involvement in many cancers, particularly in activating ECM‐related pathways that alter tumor stiffness." (PMID 40988561, 2026).
renal carcinoma (1 paper, 2010). A carcinoma arising from the epithelium of the renal parenchyma or the renal pelvis. "At the genomic level, activation of transcription of CGB, CGB5 and CGB8 genes has been associated with malignant transformation of non-trophoblastic cells (breast, bladder, prostate, thyroid, testis and renal cancer)." (PMID 20488225, 2010).
urothelial carcinoma (1 paper, 2025). A malignant neoplasm derived from the transitional epithelium of the urinary tract (urinary bladder, ureter, urethra, or renal pelvis). "We first wondered how frequently CGB7 is coexpressed with CGB3, CGB5, CGB8, and CGA in urothelial carcinoma." (PMID 40501795, 2025). "Further evaluation of expression of these genes in the TCGA urothelial carcinoma cohort revealed that while tumors tend to co-express CGB3, CGB5, and CGB8, CGB7-expressing tumors cluster independently, suggesting that CGB7 is less frequently co-expressed with CGB3, CGB5, and CGB8." (PMID 40501795, 2025).
cancer (5 papers, 2017 to 2026). A tumor composed of atypical neoplastic, often pleomorphic cells that invade other tissues. "This novel observation extends the known biological role of CGB8 and highlights its potential significance in tumor stiffness across multiple cancer types." (PMID 40988561, 2026). "We sought to systematically evaluate the expression patterns of each functional CGB gene (CGB3, CGB5, CGB7, and CGB8) across 20 distinct cancer types utilizing gene expression data from The Cancer Genome Atlas (TCGA)." (PMID 40501795, 2025). "We conclude that both type-I-encoding (CGB7) and type-II-encoding (CGB3, CGB5, and CGB8) CGB genes are expressed in human urothelial cancer cells and that CGB proteins are stable as free beta subunits and are secreted from cancer cells." (PMID 40501795, 2025). "Analysis of mRNA derived from placentas and cancer tissues pointed to a twenty fold higher transcriptional activity of CGB5 compared to CGB3 or CGB8." (PMID 31362717, 2019). "Numerous studies have demonstrated that beta-hCG-encoding genes are expressed in various cancers, but expression of these genes (CGB3, CGB5, CGB7, and CGB8) across diverse cancers has not been systematically evaluated." (PMID 40501795, 2025).
tumor (3 papers, 2025 to 2026). "We first tested whether the associations between CGB7 and CD8+ T cell infiltration and tumor subtype are upheld independently of CGB3, CGB5, and CGB8 expression." (PMID 40501795, 2025). "CGB8, a glycoprotein hormone, is known for activating ECM‐related pathways that enhance tumor migration and invasion." (PMID 40988561, 2026). "Comparing expression of each CGB gene in tumor and matched normal peritumoral tissues across these datasets elucidated extensive cancer-specific expression of CGB3, CGB5, CGB7, and CGB8 across cancer types." (PMID 40501795, 2025).
CGB8 also shares sentences with these, for which no sentence is quoted: intrauterine growth restriction (1 paper); Miscarriage (1).